ALK (ALK receptor tyrosine kinase)
Diseases named in the same sentence as ALK in open-access papers (continued):
Sharing a sentence is not in itself a finding about the gene and the disease.
tumor (continued). "In keeping with the concept of mutual exclusiveness of classic mutated driver genes, none of the four EGFR-positive patients who also underwent ALK-testing had an ALK-translocated tumor." (PMID 29100434, 2017). "IMTs with metastasis and/or recurrence were ALK-negative and exhibited elevated PD-L1 expression (positive tumor cells: 70.0% vs. 21.3%, P = 0.023; H-score: 107.5 vs. 26.3, P = 0.005)." (PMID 29163763, 2017). "Moreover, as shown with other anti-tumor treatments, the pattern of change in CTC count seems to correlate with the tumor response to ALK TKI." (PMID 29312651, 2017). "Strong ALK (5A4) protein expression in vascular co-option components was observed in tumor periphery areas adjacent to non-neoplastic brain tissues." (PMID 28837676, 2017). "This tumor was EGFR (epidermal growth factor receptor), ALK (anaplastic lymphoma kinase), KRAS (V-Ki ras2 Kirsten rat sarcoma viral oncogene homolog), ERBB2 (erb-b2 receptor tyrosine kinase 2), and B-Raf (V-raf murine sarcoma viral oncogene homolog B1) wild-types." (PMID 28915906, 2017). "Using RT-PCR and FISH methods, ALK gene rearrangement was confirmed in three adenocarcinoma patients (6.25% of all patients, 2 female and one male, non-smoking patients) who expressed abnormal ALK protein on 60%-80% of tumor cells." (PMID 28969070, 2017). "Oncogenes ALK, ROS1, RET and MET have been characterized as indicators for tumor growth." (PMID 28716024, 2017). "Levels of another tumor suppressor miRNA, miR-150 (mentioned in Section 2.3.1), were also reduced in the NPM/ALK(+) ALCL cell lines and biopsy specimens as a consequence of DNA hypermethylation, with DNA hypermethylation-mediated miR-150 repression also shown to require ALK-dependent pathways." (PMID 28771164, 2017). "ALK expression was absent in the metastases of the 16 patients with no ALK expression in their primary tumours." (PMID 28887531, 2017). "A total of 2,014 patients with stage IV NSCLC without known EGFR or ALK genomic tumor aberrations initiated systemic anticancer therapy, 22% with squamous and 78% with nonsquamous histology." (PMID 28644837, 2017). "All reported cases are ALK-negative, and the tumor is more frequently confined to the fibrous capsule." (PMID 29259783, 2017). "No discordant case of ALK expression was observed between the primary tumours and their corresponding lymph node metastases." (PMID 28887531, 2017). "It will be interesting to test whether a more potent ALK inhibitor, such as PF06463922, in combination with CGM097 or other MDM2 antagonists can delay or prevent tumor regrowth after treatment termination." (PMID 28425916, 2017). "Moreover, negligible levels of miR-26a were detected in ALK(+) ALCL cell lines (KARPAS-299 and DEL) and tumor samples." (PMID 28771164, 2017). "Indeed, in a xenogeneic NSG mouse model for NB, human ALK CAR T cells can eradicate ALK-positive tumors; both tumor antigen and receptor density governs the efficacy of these CAR T cells." (PMID 29225605, 2017). "No mutation was observed by direct sequencing of the ALK gene for exons 23, 24, and 25 in GSC and tumor samples." (PMID 28960893, 2017). "In the cells with ALK fusion, it has illustrated that dimers can be activated abnormally by aberrant receptors, which can activate the downstream signaling pathway PI3K-AKT and drive aberrant proliferation of tumor cells." (PMID 29152079, 2017). "Of the 3,661 patients with stage IV NSCLC without known EGFR or ALK genomic tumor aberrations or NSCLC NOS histology, 2,904 (79%) patients had at least one record of first-line chemotherapy." (PMID 28644837, 2017). "This CD30-expressing neoplasm is not distinguishable from its ALK-positive counterpart on morphologic grounds, except for the absence of ALK expression." (PMID 29259783, 2017).
tumor (continued). "Further, our results demonstrated that ALK signaling involves the activities of N-myc, Sox4, Sta3, and Akt, which together promote increases in tumor neovascularization under non-hypoxic conditions and cell proliferation." (PMID 28837676, 2017). "Greater PD-L1 expression was observed in IMTs with tumor necrosis and metastasis/recurrence, which were also negative for ALK rearrangement." (PMID 29163763, 2017). "Large group of patients without PD-L1 expression on tumor cells was identified among patients with common EGFR mutations and ALK rearrangement." (PMID 28969070, 2017). "Indeed, miR-150 overexpression led to a drastic inhibition of cell growth and tumor formation through repression of its downstream target MYB, a master regulator of proliferation in ALK(+) ALCL cells." (PMID 28771164, 2017). "Compared with ALK-negative patients, ALK-positive tumours were more likely to show lymph node metastases (p < 0.001)." (PMID 28887531, 2017). "The quest to find tumours dominated by a unique molecular alteration that could be targeted as effectively as in the case of EGFR and ALK mutants is a fast evolving field." (PMID 27350784, 2016). "Although caution is warranted due to a lack of head-to-head comparison, this tumor response rate is comparable with those observed in other second-generation ALK inhibitors, such as ceritinib and alectinib, in crizotinib-resistant NSCLC patients." (PMID 26966027, 2016). "However, if a rearrangement would lead to a frameshift mutation or to a non-expressed ALK variant the antibody would not identify the tumor as “positive”, although the sample could be positive by FISH and, thus, be eligible for Crizotinib therapy, and vice versa." (PMID 26784235, 2016). "ALK-positivity by IHC of this ERMS was observed as a strong positive membrane decoration in the anaplastic component and a more common cytoplasmic staining in all the remaining tumor cells." (PMID 27385213, 2016). "Treatment recommendations from the NCCN for patients with ALK-positive NSCLC mirror those for EGFR-mutant NSCLC: If the tumor is ALK-positive and the patient has not started systemic treatment, begin treatment with an oral targeted therapy." (PMID 29282427, 2016). "Although an ALK immunohistochemistry assay has been validated as an effective screening tool, the correlation between RET fusion and RET immunohistochemistry was shown to be relatively low for some tumor types." (PMID 26909603, 2016). "Interestingly, in a human sample of our collection where we had ALK-rearranged NSCLC and adjacent normal lung, we detected lower staining of ESRP1 protein in tumor cells than in the adjacent normal epithelial cells." (PMID 27119231, 2016). "Subsequently, a mechanism has been proposed whereby in a murine mimic of ALK+ ALCL transient expression of a functional TCR is required for thymic emigration of incipient, thymic-resident tumor cells, but the TCR is then downregulated for peripheral lymphomagenesis." (PMID 27705804, 2016). "We and another group reported the detection of ALK-rearrangement in CTCs ISET-enriched by filtration in NSCLC patients with an ALK-rearranged tumor as well ROS1-rearrangement in CTCs from NSCLC patients with an ROS1-rearranged tumor." (PMID 27417942, 2016). "His tumour was wild type for EGFR, KRAS and ALK, but did display MET positivity by IHC." (PMID 26883990, 2016). "Hence, we randomly selected six primary tumour samples, which were diagnosed as stage 3 or 4, and then immunohistochemically investigated the expression patterns of NLRR1 and ALK in the specimens." (PMID 27604320, 2016). "In contrast, ALK-negative tumor cells and normal peripheral blood mononuclear cells were insensitive to P36." (PMID 25950466, 2015). "In addition, another mechanism of ALK-dependent resistance occurs upon activation of alternative signaling pathways via EGFR, KIT, or KRAS with known tumor promoting properties." (PMID 26517679, 2015).
tumor (continued). "Although no expression of CD70 was found in biopsies showing ALK translocations and resistance or activating EGFR mutations, the biopsy with a T790M mutation revealed CD70 positivity in the tumor cells." (PMID 25951351, 2015). "Based on the presence or the absence of ALK translocation, the tumor is classified into either ALK-positive or -negative-ALCL." (PMID 26134389, 2015). "This study is the first to describe the in vitro activity of crizotinib in RMS tumours, this suggesting that this molecule may be a potential therapeutic agent that effectively controls ARMS growth by inhibiting ALK, MET and IGF1R pathways." (PMID 26445453, 2015). "ALK inhibitor is a promising treatment for this aggressive tumor regardless of its potential acquired resistance." (PMID 26178751, 2015). "The inhibition of tumor derived cell line from our EML4-ALK CRC patient by two separate ALK inhibitors is encouraging and provides pre-clinical rationale for enrolling ALK-rearranged CRC patients onto clinical trials with ALK inhibitor." (PMID 26172300, 2015). "We show that several of these ALK-derived peptides are proapoptotic for ALK-expressing, but not ALK-negative, tumor cells." (PMID 25950466, 2015). "Interestingly, recent studies also reported discordance between ALK CNG (or amplification) on FISH and ALK protein expression on IHC in various tumor tissues, and ALK IHC results were similarly not correlated with ALK CNG in the present study." (PMID 25803816, 2015). "This ALK dependence of P36-induced cytotoxicity was further demonstrated in oncogenic ALK-transfected Jurkat25 and SKN-AS cells, and other ALK-negative normal or tumor cells." (PMID 25950466, 2015). "This, no doubt, was initiated in hopes the scattered ALK positivity initially present in histologic sections would be inhibited, leading to regression and death of the tumor." (PMID 25763286, 2015). "Numbers and percentages of ALK-rearranged cells in tumor and in CTCs of ALK-positive and ALK-negative patients." (PMID 25414829, 2014). "Furthermore, tumor cells in ALCL are consistently immunoreactive for CD30 and usually immunoreactive for CD3 and ALK." (PMID 25364423, 2014). "Following ALK immunohistochemical staining, due to missing cores or the absence of tumor in the cores, complete results for all three antibodies were available for 105 cases." (PMID 25188507, 2014). "Advanced disease stage (p = 0.018) and larger tumor size (p = 0.037) were more frequent in the ALK rearrangement-positive group than in ALK rearrangement-negative patients." (PMID 24885886, 2014). "CTCs harboring an isolated red signal pattern were never detected in ALK-positive patients, even when isolated red signals were exclusively present in the tumor biopsies." (PMID 25414829, 2014). "The spindle cells were positive for both ALK and KIT, and it was thus difficult to determine whether the tumor was an IMT or a GIST." (PMID 24938355, 2014). "The diagnosis of ALK rearrangement can be performed by fluorescence in situ hybridization (FISH, which is considered as the gold standard), immunohistochemistry (IHC), or reverse transcriptase-polymerase chain reaction (RT-PCR) on these tumor samples." (PMID 25414829, 2014). "Pathology, tumor size, tumor disappearance rate, and the EGFR and ALK markers were analyzed." (PMID 24885886, 2014). "With IVA, there was four bone-related processes brought front only in the case of the tumour tissue—“myelopoiesis of bone marrow” (NPM1, RARA), “quantity of trabecular bone” (CREBBP, SMO), “outgrowth of bone marrow cells” (ALK) and “inflammatory response of bone marrow-derived macrophages” (RELA)." (PMID 25496518, 2014). "The reason for ALK FISH positive tumors do not show positivity in all tumor cells is mainly that there exists false negative rate." (PMID 24667320, 2014).
tumor (continued). "Furthermore, H3122 forms papillary structures in vitro, which are abolished by treatment with ALK tyrosine kinase inhibitor (TKI), suggesting some form of hierarchy among the tumor cells." (PMID 25238228, 2014). "A total of 310 patients had successful IHC stain for detection of ALK protein expression, since 2 patients without tumor part in the tissue sections were excluded." (PMID 23951022, 2013). "In 5 out of 20 of ALK-positive cases by IHC, the ALK FISH results were not interpretable because of no or weak FISH signal and loss of tumor tissue." (PMID 23741400, 2013). "However, rearrangements involving ALK have been documented in pulmonary and extrapulmonary IMTs, supporting the contention that IMT is a neoplasm." (PMID 24273608, 2013). "mRNA expression of the ALK gene was not significantly higher in the 20 tumor samples in comparison to the 5 normal breast tissue samples (p > 0.05, t test)." (PMID 24156086, 2013). "In fact however, when we compared the number of chromosome arm altered between pathological stage I and II-IV, total number did not increase in pathological stage II-IV, though only ALK fusion-negative tumours showing significant elevation of chromosomal gain." (PMID 23289484, 2013). "The tumor did not overexpress the anaplastic lymphoma kinase (ALK) protein, indicating a lack of ALK rearrangement." (PMID 23761833, 2013). "Overall aberration numbers (gains + losses) of chromosomal alterations were 8.42 and 9.56 in tumours with and without ALK fusion, respectively, the difference not being statistically significant, although patterns of gain and loss were distinct." (PMID 23289484, 2013). "The present case was ALK positive, but within the follow-up time of three years, the tumor has not shown any signs of recurrence." (PMID 23691372, 2013). "There were no oncogene-related loci with more gains and no suppressor gene-related loci with more losses in tumours with ALK fusion." (PMID 23289484, 2013). "During a proteomic pathway analysis, the ALK pathway was found to be activated in 3 different IBC cell lines, and later genomic experiments showed that the ALK gene was amplified in IBC cell lines and in 9 of the 12 tumor samples analyzed." (PMID 24156086, 2013). "Other genes identified in our screen, such as ALK and PDE4D, increase tumor cell growth and protect from apoptosis, and may therefore promote resistance through these mechanisms." (PMID 23442791, 2013). "ALK fusion positive tumours are more common among non-smokers and the younger population, similar to those with EGFR mutations." (PMID 23289484, 2013). "Moreover, the treatment of ALK+ NSCLC with Hsp90 inhibitors resulted in Erk dephosphorylation as well as the degradation of Akt and the EML4-ALK oncoprotein in these tumours." (PMID 22681779, 2012). "Screening the 15% of the population with advanced stage NSCLC who have tumours with adenocarcinoma histology who have never smoked should, therefore, capture 56% of the ALK rearrangements present in the adenocarcinoma population." (PMID 22374459, 2012). "Second, the distribution of cell positivity by FISH is diffuse; there are no discrete foci of ALK rearrangements within a tumour." (PMID 22825000, 2012). "Anaplastic lymphoma kinase-(ALK-) positive large B-cell lymphoma (ALK+ LBCL) was first described by Delsol and colleagues in 1997 and is now listed as a distinct entity in the 2008 WHO Classification of Tumours of Haematopoietic and Lymphoid Tissues." (PMID 22474449, 2012). "It is noteworthy that proliferation of the tumor cells is not affected by either by depletion of ALK or by blockade with an antibody." (PMID 23267434, 2012).
tumor (continued). "However, samples assigned to the p4 cluster showed a significantly lower expression of MYCN and ALK compared to the MNA-specific cluster p3, which indicate an alternative progression pathway within tumours assigned to the fourth cluster." (PMID 21492432, 2011). "Although both compounds inhibited tumor growth without side effects, only BP7033Br ALK abrogated tumor angiogenesis and D3H2LN cells-induced metastases formation." (PMID 19262688, 2009). "Pathological biopsy revealed that the tumor was composed of monomorphic spindle cells arranged in a fascicular growth pattern with extensive necrosis and coexpression of S100 and CD34; subsequently, PLEKHH2::ALK fusion was identified via next-generation sequencing (NGS)." (PMID 41672777, 2026). "Moreover, the combination of JAK1/2 inhibitors with TKI therapy and the combined use of ALK and STAT3 inhibitors can regulate the immune response and restore the sensitivity of tumor cells to treatment, thereby overcoming the resistance driven by AST and improving the treatment outcome." (PMID 40568576, 2025). "Moreover, the combination of anlotinib with benmelstobart produced encouraging tumor responses in advanced NSCLC lacking EGFR or ALK alterations, with generally manageable toxicities." (PMID 40908570, 2025). "The ALK (D5F3) companion diagnosis was negative (tumor cells, positive control + negative control)." (PMID 41383499, 2025). "Secondly, the analysis did not incorporate genetic markers (e.g., N-MYC, ALK), which may act as confounding factors and limit the interpretation of tumor heterogeneity." (PMID 40786507, 2025). "Metastatic or recurrent NSCLC without EGFR or ALK genomic tumor aberrations." (PMID 40342408, 2025). "Consistent with our in vitro results, tumor tissue prior to ALK inhibition therapy showed negative BIM staining, whereas the histological section removed during lorlatinib treatment showed some areas with a slight increase in BIM expression, although this increment was not as high as expected." (PMID 40113795, 2025). "Furthermore, since CGP is not yet routinely used across all tumor types, it is not known how representative the patient population is of the wider population of patients with ALK fusion-positive solid tumors." (PMID 40338218, 2025). "This is based on the fact that targeted therapies are available for these patients (although not in the neoadjuvant setting), and that ALK‐/EGFR‐altered tumours have been shown to have a poor response to IO therapy, leading to their exclusion from the CheckMate 816 trial." (PMID 40911027, 2025). "Of eight ALK-negative tumor samples, seven(88%) showed PD-L1 positivity." (PMID 40877871, 2025). "ALK-negative tumours lack this target and may pursue a more aggressive course, with higher metastatic risk." (PMID 40980125, 2025). "Finally, T-cytotoxic lymphocytes (CD8+) and tumor-associated macrophages (CD163+) were evaluated in samples with EGFR and KRAS mutations, ALK rearrangements and LUAD with no genetic findings." (PMID 40809430, 2025). "SK-N-AS, which exhibits very low ALK surface expression, did not demonstrate complete and sustained tumor regressions but the transient anti-tumor activity suggests the presence of bystander cytotoxicity and potential to provide adjuvant therapeutic benefit in low ALK-expressing tumors." (PMID 40813394, 2025). "We assessed whether LIPI, in combination with baseline clinical characteristics, can guide first-line treatment selection between pembrolizumab (P) and pembrolizumab plus platinum-based chemotherapy (PCT) in patients with PD-L1 tumor proportion score (TPS) ≥ 50% and EGFR/ALK/ROS1 wild-type." (PMID 40429538, 2025). "Notably, IL10 may also have a direct effect on ALK-positive ALCL tumor cells because the ALCL cell line, SU-DHL1, expresses IL10 receptor subunits A and B in an ALK-dependent fashion." (PMID 41469691, 2025).